CTCF (CCCTC-binding factor)
Diseases named in the same sentence as CTCF in open-access papers (continued):
Sharing a sentence is not in itself a finding about the gene and the disease.
testicular tumour (1 paper, 2025). "CTCF and its paralogues have been previously identified in testicular tumour cells." (PMID 39809819, 2025).
thalassemia (1 paper, 2019). An inherited blood disorder characterized by a decreased synthesis of one of the polypeptide chains that form hemoglobin.
uterine corpus endometrial carcinoma (1 paper, 2018). A endometrial carcinoma (disease) that involves the body of uterus. "To ascertain the impact of CTCF haploinsufficiency in the context of human cancers, we examined a uterine corpus endometrial carcinoma (UCEC) dataset from The Cancer Genome Atlas, which exhibits CTCF genetic alterations in 45 out of 232 patient samples (~19%)." (PMID 30513694, 2018).
uterine tumors (1 paper, 2020). "Although the mutational frequency of CTCF is low in prostate and breast (1–2%), mutation of CTCF occurs at higher rates in other cancers (e.g., 20% in uterine tumors of the TCGA), contributing to alterations in the epigenetic landscape of these cancers." (PMID 32503656, 2020).
cancer (277 papers, 2004 to 2026). A tumor composed of atypical neoplastic, often pleomorphic cells that invade other tissues. "Strikingly, CTCF-bound sites and chromatin loop anchors are frequently damaged or mutated in cancer." (PMID 41338928, 2026). "Supporting a direct role of CTCF in the DDR, CTCF is a tumor suppressor gene that is mutationally constrained in the germline, but frequently mutated in cancer." (PMID 41338928, 2026). "For example, in one child there was a germline deletion of chromosome 16q which encompasses the recessive cancer and putative Wilms predisposition gene, CTCF." (PMID 39665570, 2025). "The initial strategy for CTCF cancer mutation screening was employed in K562 cells by introducing HA-tagged CTCF mutant variants via lentiviral transduction to distinguish transgenic CTCF from endogenous CTCF." (PMID 41511335, 2025). "On the other hand, removal of CTCF sites at TAD boundaries can result in ectopic gene activation in cancer cell lines and has been associated with Mendelian disease." (PMID 40436628, 2025). "Complementation assays provide a robust framework for investigating domain-specific protein functions and cancer-associated mutations, as demonstrated by studies of CTCF." (PMID 41511335, 2025). "BORIS, a methylation-independent DNA-binding protein and paralog of CTCF, has been linked to increased tumor size and grade in several cancer types, potentially contributing to oncogenic transcription by counteracting the function." (PMID 40725442, 2025). "Using a combination of imaging, structural and molecular approaches we haveexamined the impact of nine, high frequency cancer associated CTCF mutations in ZFs thatmake contact with the core consensus binding motif." (PMID 39070636, 2024). "In humans, CTCF mutations have been implicated in various cancers and also contribute to neurological disorders." (PMID 38658702, 2024). "This is hinted at by the fact that in some cancers, where the DNA methylome is broadly misregulated, there are notable examples of 5meC accumulation leading to CTCF loss resulting in oncogene expression, or repression of a tumor suppressor." (PMID 39180406, 2024). "In a recent study, it is found that CTCF/cohesin binding sites are a major mutational hotspot in the cancer genome." (PMID 38463168, 2024). "Faseela EE (NCBS, Bengaluru), PhD student, linked CTCF/Cohesin binding sites to replication stress during S phase, possibly leading to genomic instability in cancers." (PMID 39140283, 2024). "The absence of CTCF in mice is lethal in the early embryo, whereas heterozygous deletions of the protein present predisposition to cancer, indicating that CTCF plays an essential role in development and cell identity." (PMID 39180406, 2024). "Second, besides large chromatin compartments, we observed that HBV specifically changed boundaries of vulnerable TADs with low TAD isolation or CTCF insulation scores, which was associated with cancer metastasis." (PMID 37063858, 2023). "This suggests that aberrant cohesin-binding events can rarely be attributed to somatic mutations, which is similar to the findings for cancer-specific CTCF." (PMID 37283809, 2023). "Overall, our atomic-level biophysical findings help better understand the molecular mechanisms involved in the misregulation of gene expression and the development of cancer due to CTCF mutations." (PMID 37047368, 2023). "Such an analysis, enhanced with the usage of CTCF ChIA-PET data, showed that disruptions of the insulators (that are creating the domains) by motif mutations and improper binding of CTCF (and, by that, diminish of the loop) lead to cancer development." (PMID 37474564, 2023). "Other studies conducted in cancer cell models have focused on the functional impact of CTCF mutations that disrupt the central ZF DNA-binding domain." (PMID 37324587, 2023). "We have investigated the atomic-level effects of common CTCF mutations associated with human cancers by molecular dynamics simulations." (PMID 37047368, 2023).
cancer (continued). "While it is clear that CTCF mutations are frequently identified in cancer, the degree to which such mutations alter CTCF’s binding capabilities and structure at the atomic level is not well understood." (PMID 37047368, 2023). "To date, studies investigating the impact of CTCF mutations on DNA binding, gene expression and chromatin structure are focused on mutations found in cancer." (PMID 37324587, 2023). "To this end, we compare all-atom molecular dynamics simulations of a wildtype CTCF–DNA complex to those of eight different cancer-linked CTCF mutant sequences." (PMID 37047368, 2023). "CTCF variants are frequently identified in cancer; and CTCF haploinsufficiency is a known mechanism of tumorigenesis, highlighting CTCF as a tumor suppressor gene." (PMID 37324587, 2023). "CTCF/cohesin-binding sites (CBS) are mutational hotspots in cancer (found primarily in gastrointestinal cancers), and somatic alterations to CBSs have been linked to altered expression of nearby gene, likely due to altered CTCF-mediated looping." (PMID 38020908, 2023). "Because single-residue CTCF mutations have been linked to the development of a variety of cancers in humans, we aim to better understand how these mutations affect the CTCF structure and its interaction with DNA." (PMID 37047368, 2023). "TAD changes arise in the cancer genome through a variety of mechanisms including somatic mutation, CTCF binding site alterations, CTCF inferiority." (PMID 36468037, 2022). "Further sustaining the view of a tumour suppressive action of CTCF, its loss leads to upregulation of the Programmed Cell Death Protein 1 (PD‐L1) which aids cancer cells to evade immune system surveillance." (PMID 35993175, 2022). "In order of significance, sites associated with CCCTC-binding factor (CTCF) topped the list—a TF commonly mutated in cancer and known to normally function widely in controlling chromatin architecture." (PMID 34791221, 2022). "Together, the results indicated that the cancer-associated arginine mutations in the CTCF DBD interfered with the DNA-binding and insulation functions of CTCF." (PMID 36117989, 2022). "It is now established that mutation of CTCF, the only insulator protein found in humans, predisposes cells to cancer formation through increased rates of unrepaired DNA damage." (PMID 36197938, 2022). "Across all cancer types, the mutation rate of CTCF is 2% overall, with the mutation considered to be oncogenic in half the cases." (PMID 36171609, 2022). "Here, we reveal that a common chromosomal aberration across cancers, CCCTC-binding factor (CTCF) copy number loss, potentiates cell invasion by reorganizing chromatin contacts at the level of sub–topologically associated domain (subTAD) interactions." (PMID 36037342, 2022). "We reveal that the CTCF ZF domain is significantly mutated in cancer, with ZF-specific missense mutations impacting CTCF’s anti-proliferative capacity, DNA-binding and gene regulatory activities." (PMID 34657170, 2021). "This includes changes in CTCF protein function, cancer-risk single nucleotide polymorphisms, viral integration, and hormonal response as part of the mechanisms that lead to the acquisition of enhancers or super-enhancers." (PMID 35011637, 2021). "The stress-regulated activity of CTCF is uncoupled in persistently stressed, epigenetically re-programmed “variant” HMECs and certain cancer cell lines." (PMID 33411704, 2021). "Given frequent allelic variations and somatic mutations in CTCF, it would be important to establish links between aberrant CTCF-mediated AS and cancer." (PMID 34181707, 2021). "DNA-binding sites of the master transcriptional regulator and chromatin architectural protein CTCF (CCCTC-binding factor) are enriched in somatic mutations in multiple cancer types." (PMID 33941236, 2021). "Both CTCF and cohesion-binding sites suffer an exceptionally high mutational rate in cancer genomes." (PMID 34638453, 2021).
cancer (continued). "Despite many CTCF mutations having been identified in numerous cancer types, the functional consequences of these mutations have not been thoroughly examined." (PMID 34657170, 2021). "Understanding how somatic CTCF ZF mutations affect chromatin topology globally will be the next frontier in understanding the molecular pathophysiology of cancer." (PMID 34657170, 2021). "We analysed cancer genome sequencing databases and published mutation data to determine the distribution, frequency and nature of somatic mutations occurring in CTCF." (PMID 34657170, 2021). "In this work, we described an improved version of svMIL, svMIL2, to predict pathogenic TAD-boundary and CTCF-loop disrupting non-coding SVs from WGS cancer genomes with paired whole transcriptome sequencing data." (PMID 34257393, 2021). "We previously showed that the aberrant BORIS expression in cancer cells is associated with the execution of a germline-like transcription program through CTCF and BORIS heterodimerization at the promoter regions of cancer-testis genes." (PMID 34158481, 2021). "The loss of CTCF boundaries causes inappropriate enhancer–promoter interactions and dysregulated local gene expression in cancer." (PMID 33924956, 2021). "In other contexts, CTCF loss mediates unique DNA hypermethylation surrounding CTCF binding sites in a variety of human cancers." (PMID 34019588, 2021). "Whilst isolated somatic CTCF mutations were first identified in some solid tumours, numerous cancer genome studies since have highlighted the impact and prevalence of CTCF mutation in multiple cancers." (PMID 34657170, 2021). "CTCF is also a tumour suppressor frequently mutated in cancer, however, the structural and functional impact of mutations have not been examined." (PMID 34657170, 2021). "CTCF mutations occur prominently in cancers arising in the endometrium and breast (~ 48%), consistent with mutant CTCF being classified as a pan-gynaecological driver of cancer." (PMID 34657170, 2021). "In this study, we performed a meta-analysis of all publicly available cancer mutation data for CTCF and showed a significant enrichment of missense mutations occurring in CTCF’s ZF DNA binding domain." (PMID 34657170, 2021). "We performed molecular and structural characterisation of five cancer-specific CTCF missense zinc finger (ZF) mutations occurring within key intra- and inter-ZF residues." (PMID 34657170, 2021). "Since then the functional characterisation of CTCF ZF mutations has been limited, despite many landmark cancer genome studies reporting hundreds of missense somatic CTCF ZF mutations." (PMID 34657170, 2021). "The constitutively bound CTCF sites matching the DNA motifs were strongly enriched in mutations in ten cancer types and the pan-cancer cohort." (PMID 33941236, 2021). "CTCF mutations affecting the DNA-binding zinc finger domains compromise binding to the genome and can occur in cancer or abnormal limb development." (PMID 32933554, 2020). "CTCF is integral to cell survival as total knockouts in mice are lethal in early embryogenesis and heterozygous knockouts are predisposed to cancer." (PMID 32933554, 2020). "We propose that CTCF loss provides a unique contribution to the cell-type specific chromatin landscape in cancer." (PMID 32503656, 2020). "Using large-scale genome analysis technologies, we report novel insights into the role of CTCF functional loss in directing DNA hypermethylation in multiple human cancer types." (PMID 32503656, 2020). "In the prostate, the Igf2-H19 locus experiences DNA hypermethylation with CTCF downregulation at a series of intergenic CTCF sites resulting in imprinting loss during aging and cancer development." (PMID 32503656, 2020). "Mutations in CTCF and at CTCF binding sites have previously been associated with multiple forms of cancer, putatively disrupting the epigenetic regulation of proliferation." (PMID 32374727, 2020).
cancer (continued). "Despite evidence linking CTCF to the protection of epigenetic states through barrier insulation, the impact of CTCF loss on genome-wide DNA methylation sites in human cancer remains undefined." (PMID 32503656, 2020). "The deregulation of DNA-methylation is universally associated with various cancers, and we have earlier shown the role of DNA methylation-mediated CTCF recruitment in the regulation of CD45 alternative splicing in lymphocyte development." (PMID 31675998, 2019). "Cancer genome sequencing reveals diverse acquired mutations in CTCF, which we have shown functions as a tumour suppressor gene." (PMID 30513694, 2018). "We conclude that genes other than MYC are likely regulated by CTCF-bound enhancer-docking sites and that these include multiple cancer-associated genes." (PMID 29641996, 2018). "CTCF hemizygous mice are more susceptible than WT mice to spontaneous cancer development, as well as radiation- and chemically-induced cancers." (PMID 30513694, 2018). "Mutations in the binding site for the zinc finger protein CTCF have already been described, and we find that tapRNAs overlap CTCF sites that are found mutated in cancer." (PMID 29540241, 2018). "We found evidence that for 25 tapRNAs the mutation of CTCF (19 tapRNAs) or ZNF263 (7 tapRNAs) coincides with a significant change in tapRNA expression in the equivalent cancer." (PMID 29540241, 2018). "In contrast to germline variants, somatic missense and nonsense mutations of CTCF are common in human cancers." (PMID 30086769, 2018). "CTCF has been identified as a putative driver gene in several cancer types and such loss of function is in keeping with the action of a tumor suppressor gene." (PMID 30086769, 2018). "Disruption of promoter methylation, chromatin modifications and structural changes mediated by CTCF can lead to the dysregulation of cancer-associated genes, including RARRES1, HOXA10, TERT and PTGS2." (PMID 28977939, 2017). "DNA isolated from FFPE samples was analysed using a custom Nanostring nCounter copy number variation panel of cancer-associated genes across the long arm of chromosome 16 (16q) with a particular focus on 16q22.1 where CTCF is located." (PMID 28319062, 2017). "This would add further selective pressure to favor increasingly aggressive phenotypes and a possible pathway for cancers to evolve as tumor suppressor loci become silenced in response to the loss of CTCF PARylation." (PMID 29029387, 2017). "Sporadic mutations in CTCF or defective CTCF function have been observed in various cancer types, with CTCF functioning as a tumor suppressor." (PMID 28977939, 2017). "These striking patterns of mutation differ across TFBSs and cancers, and yet a high attrition of CTCF sites is a notably general feature." (PMID 27490693, 2016). "In the present paper, we demonstrate that in cancer cells, CTCF is unable to associate with its cognate DNA-binding site in the XAF1 promoter if it is methylated, thus effectively rendering it unresponsive to well-known activators." (PMID 26443201, 2015). "Some mutations in the CTCF gene have been localized and characterized in various types of cancer, including breast." (PMID 25114808, 2014). "By analyzing data from various libraries, like miRbase and ENCODE, we show a prevalence of various cancer-related genes, miRNAs, and regulatory binding sites, such as CTCF within CFSs." (PMID 25238782, 2014). "Coding mutations in the CTCF gene affecting its DNA binding specificity have been identified in cancer samples, but lesions in its binding sites are harder to interpret." (PMID 22457641, 2012). "This 20q13 gain as well as 16q22 loss of heterozygosity (LOH) with increased BORIS expression parallels a similar association in cancers that also show CTCF haplo-insufficiency." (PMID 22168535, 2011). "CTCF, as a transcriptional repressor, has been associated with various cancers." (PMID 39589950, 2024).